KIT (KIT proto-oncogene, receptor tyrosine kinase)
Diseases named in the same sentence as KIT in open-access papers (continued):
Sharing a sentence is not in itself a finding about the gene and the disease.
tumor (continued). "In this study, we show that KIT expression in CRC induces CMS4-like features, including a high tumor stroma content, high expression of TGFβ, accompanied by partial EMT and higher regenerative capacity of the tumor cells." (PMID 35842424, 2022). "Two recent studies of lenvatinib, a kinase inhibitor acting on the VEGFR, PDGFR, FGFR, KIT, and RET pathways, have shown exciting results in reducing tumor burden in patients with recurrent/metastatic ACC." (PMID 35205740, 2022). "Since conventional markers of cancer stem cells, namely CD133, CD44, KIT, and ALDH1A1, were expressed in all the tumor clusters to a similar extent, we performed cell trajectory analysis." (PMID 35892844, 2022). "Regarding conventional markers of cancer stem cells, CD133, CD44, KIT, and ALDH1A1 exhibited similar expression in all the tumor clusters." (PMID 35892844, 2022). "Lenvatinib, confirmed as an inhibitor of VEGF receptors 1–3, FGF receptors 1–4, platelet-derived growth factor (PDGF) receptor α, KIT, and RET, selectively inhibits receptor tyrosine kinases involved in tumor growth and angiogenesis." (PMID 34527576, 2021). "Sorafenib is a multikinase inhibitor that targets the Raf/MAPK/ERK signaling pathway, interfering with the tyrosine kinases VEGFR-2/3, PDGFR-β, B-Raf, c-Raf, FGFR1, Flt3, c-KIT, RET, and p38 α, and induces tumor cell apoptosis in HCC." (PMID 33808407, 2021). "MET inhibitor cabozantinib (also inhibits VEGFR2, AXL, KIT, RET) has been studied as an inhibitor of angiogenesis and tumor growth in many tumor diseases." (PMID 34212564, 2021). "Regorafenib inhibits multiple tyrosine kinases involved in tumor angiogenesis (VEGFR1-3, TIE2), oncogenic transformation (KIT, RET, RAF1, BRAF), and shaping tumor microenvironment (PDGFR, FGFR)." (PMID 34527573, 2021). "Inhibition of KIT and PDGFRA by tyrosine kinase inhibitors has revolutionized the treatment of GISTs and demands accurate tumor classification." (PMID 35199796, 2021). "Sorafenib, approved in 2008, inhibits multiple growth tyrosine kinase receptors (PDGFRs, VEGFRs, c-KIT, and RET) and their downstream tyrosine kinase cascades (Ras, Raf, Mek, and Erk) in both tumor cells and endothelial cells." (PMID 33669204, 2021). "For instance, neutralizing antibody to KIT significantly reduced MDSC expansion and unleash anti-tumor efficacy of T cells in colon carcinoma." (PMID 33968014, 2021). "Sunitinib, a multitarget tyrosine kinase inhibitor that targets PDGFR, VEGFR, KIT, FLT-3 and RET, can inhibit not only tumor proliferation but also angiogenesis at the same time." (PMID 34778094, 2021). "Regorafenib targets VEGFR1-3, TIE2, KIT, RET, RAF, PDGFR and FGFR, among other kinases, regulating tumor angiogenesis and tumor microenvironment and showing therapeutic benefit in various malignancies." (PMID 33800796, 2021). "Regorafenib is an oral multikinase inhibitor of several protein kinases, including kinases involved in tumor angiogenesis (VEGFRs 1–3), oncogenesis (KIT, RET, RAF1, BRAF, and BRAFV600E), and development of the tumor microenvironment (PDGFR and FGFR)." (PMID 33337518, 2021). "Regorafenib is an oral MKI affecting vasculature and tumor microenvironment with targeting of specific kinase proteins (VEGFR1,2,3, PDGFR, FGFR, KIT, BRAF, and RET)." (PMID 34069999, 2021). "The mRNA expression level and prognostic significance of KRAS, BRAF, and KIT were checked using the UALCAN database, in the heatmap representation, normal tissue (n = 1), primary tumor (n = 104), and metastatic cases (n = 368)." (PMID 34769348, 2021). "A possible reason is the wide range of tumor cell targets affected (VEGF, VEGFR1–3, FGFR1–4, PDGFRα, KIT, and RET)." (PMID 34630336, 2021).
tumor (continued). "More importantly, the anti-tumor effects of bortezomib targeting cyclin D1 and Hippo/YAP will need to be evaluated in vivo in KIT-independent GISTs." (PMID 34025442, 2021). "However, several explanations might be suggested for real differences in protein expression, including the proliferative capacity of the tumor, the tumor size, the age of patient, and other proteins that might affect, directly or indirectly, the expression of c-KIT." (PMID 34439864, 2021). "Lenvatinib inhibits tumor growth by blocking several targets, including VEGFRs, PDGFRs, FGFs, SCF, PDGFR, c-KIT, and RET." (PMID 33669204, 2021). "Of note, BGJ398 used alone exhibited minor anti-tumor effects on IM-resistant xenografts, thereby suggesting the activation of FGF-signaling as a compensatory mechanism of IM resistance in KIT-inhibited GISTs in vivo." (PMID 32599808, 2020). "Immune contexture was examined in relation to driver gene (KIT, PDGFRA, K/P WT), tumor location (gastric and intestinal), and malignant potential (miniGIST and overt GIST)." (PMID 33048845, 2020). "This study comprehensively characterized 9 MGs and adenocarcinomas present in the same surgical resection specimen by analyzing the c-KIT/PDGFRα status and EBV/MSI status on both tumor types." (PMID 33335133, 2020). "It inhibits the activity of target enzymes/factors located in tumour cells (CRAF, BRAF, V600E BRAF, c-KIT and FLT-3) and in tumour vasculature (CRAF, VEGFR-2, VEGFR-3 and PDGFR-β)." (PMID 32016844, 2020). "A gene expression analysis revealed that KIT levels were significantly lower, while those of LIF were significantly higher (overexpressed), in tumor tissues, compared to those of normal tissues." (PMID 33092068, 2020). "This evidence shows that mutant KIT and PDGFRA can be detected and quantified in plasma of GIST patients, also with a predilection for patients with high tumor burden." (PMID 32024476, 2020). "Regorafenib inhibits vascular endothelial growth factor receptors (VEGFRs) to reduce the degree of islet cell inflammation and the mutant oncogenic kinases KIT, B-RAF, and RET to inhibit tumor angiogenesis and tumor cell proliferation." (PMID 32660121, 2020). "In BRAFV600E cells, KIT suppresses the RAS/MAPK pathway activity mediated by BRAF activation, and acts as a tumor suppressor." (PMID 31426590, 2019). "MCs migrate into the CCA tumor microenvironment via KIT/SCF and increase tumor progression, angiogenesis, and ECM degradation." (PMID 31766207, 2019). "GISTs WT for KIT and PDGFRA constitute a pathogenetically heterogeneous tumor group accounting for about 10–15% of GISTs." (PMID 30616628, 2019). "Our data show that in normal mammary epithelial cells, LYN kinase activity is under the strict control of the c-KIT receptor, whereas in Brca1 mutant tumor cells, LYN functions independently of c-KIT." (PMID 30590041, 2018). "Another multi-kinase inhibitor sunitinib, an anti-PDGFRα/β, VEGFR1/2/3, KIT, FLT3, CSF- b1R and RET, has been shown to decrease primary tumor proliferation and reduce tumor vasculature in cell-derived intratibial OS model in SCID mice." (PMID 29520051, 2018). "Moreover, miR-148b-3p functions as a tumor suppressor in suppressing cell proliferation, migration, and invasion through directly targeting KIT, and it could be exploited as a prognostic biomarker to predict the aggressive behavior as well as a therapeutic target in GISTs." (PMID 29661252, 2018). "For example, Src family kinases HCK, FRK and LYN are onco-homologs of PDGFRA/KIT, which interact with both PDGFRA and KIT as downstream effectors and play critical roles in tumor cell proliferation and survival." (PMID 29844492, 2018). "Within tumor tissue alone, MUC1 and KIT exhibited increased expression in patients with a low CRP compared to those with a CRP ≥5 mg/L." (PMID 30016964, 2018).
tumor (continued). "Regorafenib is a different oral MKI that potently blocks multiple protein kinases involved in tumor angiogenesis (VEGFRs 1–3, TIE2), oncogenesis (KIT, RET, RAF-1, BRAF), metastasis (VEGFR3, PDGFR, fibroblast growth factor receptor), and tumor immunity (CSF1R)." (PMID 29291014, 2017). "miR-193a-3p can suppress tumor development in humans by silencing SRSF2, HIC2, HOXC9, PSEN1, LOXL4, ING5, c-KIT, PLAU, and MCL1." (PMID 29016617, 2017). "Regorafenib, an oral mutikinase inhibitor, can inhibit activity of several protein kinases, including those involved in tumor proliferation (KIT, PDGFR and RET), tumor angiogenesis (VEGFR1-3, TIE2), and tumor microenvironment (PDGFR-B, FGFR)." (PMID 28915719, 2017). "After freshly isolating KIT+ and KIT- cells from 3 human metastatic, imatinib-resistant GISTs with high ETV4 expression, we showed that ETV4 mRNA was minimal in KIT- (i.e., non-tumor) cells." (PMID 29371979, 2017). "In reality, the REB array can be used to exclude tumours with common BRAF or NRAS mutations from further testing, allowing resources to be concentrated on sequencing cases where the driver mutation is not known, and knowledge of the KIT status of the tumour may be helpful." (PMID 28228113, 2017). "Future investigation should focus on changes to the tumor microenvironment (such as IDO expression) and systemically with therapy and evaluate combination of KIT inhibition with other checkpoint blockade agents." (PMID 28428884, 2017). "IM is an inhibitor of receptor tyrosine kinases, including the stem cell factor receptor KIT and the platelet-derived growth factor receptor alpha (PDGFRA), the main drivers of tumour development in GIST." (PMID 27999655, 2016). "Pathological examination revealed a tumor composed of viable spindle cells with 34 mitoses/50 HPF and positive CD117 (KIT) staining." (PMID 27864817, 2016). "Suppression of KIT mRNA or pharmacological inhibition of KIT signaling in GIST cells is sufficient to induce apoptosis and tumor regression." (PMID 27793025, 2016). "Previous studies have suggested that gastrointestinal stromal tumor cell-derived exosomes contain oncogenic KIT, and their transfer and uptake by the surrounding smooth muscle cells led to enhanced AKT and MAPK signaling and enhanced tumor cell invasion." (PMID 27716356, 2016). "An endoscopic biopsy was obtained from the tumor in the small intestine, with pathological results compatible with GIST (KIT+; vimentin+)." (PMID 27586263, 2016). "Combined inhibition of KIT and RACK1 inhibited growth in imatinib-resistant GIST cell lines and reduced tumor relapse in GIST xenografts." (PMID 26893362, 2016). "In several series, which have been of limited size due to the rarity of this tumor type, imatinib-induced blockade of PDGFR and KIT has shown modest activity as monotherapy, with evidence of activity in combination with rapamycin." (PMID 27200287, 2016). "Anti-tumor effects are believed to occur by several molecular mechanisms including inhibition of RAF, VEGFRs, PDGFRs, and KIT." (PMID 26583076, 2015). "IDO expression can be blocked by inhibitors of c-KIT or mTOR (downstream of the c-KIT/PI3K/AKT pathway), with resultant enhancement of anti-tumor T cell responses, but the potential role of PI3K/AKT/CREB signaling or STAT3 activation has not been addressed." (PMID 26343197, 2015). "Moreover, MM does not represent a unique tumor entity but differs due to alternative ontogenesis as, for example, mutations of KIT are more often detected in gynecological MM rather than sinonasal differing also clinically in distinct forms, a unilocular and multilocular subtype." (PMID 26161400, 2015). "We discovered that a population of NB cells, which express high level of c-KIT (c-KIThigh), a tyrosine-kinase receptor for stem cell factor (SCF), is de novo generated and dynamically maintained within the tumors to sustain tumor progression." (PMID 26682270, 2015).
tumor (continued). "By Western immunoblotting we observed expression of KIT and its main signalling mediators in all untreated UZLX-GIST9 tumours." (PMID 25132955, 2014). "We also observed low impact alteration in KIT and STK11 exclusively in the tumor group which resulted from base transversions." (PMID 25404506, 2014). "The odds ratio (OR) of c-KIT, VEGFR2 and PDGFRα positivity, adjusted for tumor characteristics, was 6.8, 3.6 and 1.3 times higher for TNBC than for non-TNBC." (PMID 25025175, 2014). "Considering the more aggressive behavior of c-KIT positive CSEM in men, close clinical monitoring would be advisable for dogs with this type of tumor." (PMID 25096628, 2014). "In this tumor EGFR amplification was seen across all tumor regions, while amplification of both PDGFRA and KIT was detected in two of five regions." (PMID 25608559, 2014). "Microscopic analysis revealed a predominantly spindle cell morphology and diffuse CD117 (KIT) immunoreactivity in the original GIST metastasis and in ex-mouse tumours, characteristics also observed in the original primary gastric GIST lesion." (PMID 25132955, 2014). "The combination of low-dose NVP-AUY922 with rapamycin had comparable effects on reducing KIT expression, increasing MAP1LC3B puncta and tumor necrosis, and inhibiting tumor growth as high-dose NVP-AUY922 did in GIST430 xenograft model." (PMID 25375091, 2014). "Western immunoblotting showed a mild reduction in KIT and AKT activation only in regorafenib treated tumours." (PMID 25132955, 2014). "Those tumours with concurrent PDGFRA and KIT amplification fell in between these figures (3/7, 42.9%)." (PMID 23990986, 2013). "PDGFRA, KIT, and KDR genes that are located on the amplified segment 4 q12 probably play an important role in tumor biology due to their increased expression of receptors and their ligands." (PMID 23537212, 2013). "Subsequently, we confirmed well-characterized oncogenes among tumor-related loci (such as EGFR and KIT) and detected novel genes that gained chromosome sequences (such as AASS, HYAL4, NDUFA5 and SPAM1) in both LGG and HGG." (PMID 23451178, 2013). "The tumor tissues were sequenced for KIT, BRAF, NRAS, and GNAQ mutant genes and patients with amplification or overexpression of KIT were treated with Sunitinib." (PMID 23515890, 2013). "The natural ligand for KIT, SCF, conferred anti-tumor specificity for the anti-KIT CIR and T cells were transduced with high levels of efficiency." (PMID 23433424, 2013). "In this case, tumor cells showed diffuse and strong positivity for CD117 (KIT) and CD34, which was consistent with a diagnosis of GIST." (PMID 22988538, 2012). "The BRAF and KIT genotypes of the isolated CTC were then analysed; the results showed that the genotypes of the CTC differed from those of the primary tumours and metastatic lesions." (PMID 22281663, 2012). "In KIT+ NSCLC, expression of CD117 provides a potential link between a large proportion (44%) of tumor cells and their less prevalent normal lung counterpart, the multipotent lung stem cell." (PMID 23285214, 2012). "In our study, message for KIT was detected in all primary and metastatic AGASACA, as well as TC tumor samples." (PMID 22630170, 2012). "We examined expression of the 3 receptor genes PDGFRA, KIT, and KDR, because of their central function in tumor biology and their significance as therapeutic targets." (PMID 20686603, 2010). "Next, the cell cycle in tumor cells treated with NPRL2 and cisplatin was analyzed by flow cytometry (FACS) with use of a APO-BRDU KIT." (PMID 20700484, 2010).
tumor (continued). "In fact, GISTs are highly vascularised tumours, and VEGF expression has been postulated to be a KIT-genotype-independent adverse prognostic indicator for early treatment failure and poor survival of GIST patients on imatinib therapy." (PMID 19943934, 2009). "The tumor cells showed strong cytoplasmic staining for the immunohistochemical markers vimentin and CD34 and focally and weak reaction for KIT." (PMID 19830214, 2009). "Histologically, the tumor was composed of spindle cells, and was positive for c-KIT (CD117), slightly positive for alpha-smooth muscle actin (SMA), and S-100 protein positive." (PMID 18664259, 2008). "Immunohistochemically, the tumor was positive for myeloid stem cell antigen (CD34), weakly positive for c-KIT (CD117) and slightly positive for neuron-specific enolase (NSE), but negative for cytokeratin (CK), alpha-smooth muscle actin (SMA) and S-100 protein." (PMID 17565683, 2007). "Immunohistochemical analyses of these tumors have shown that the tumor cells frequently express KRT5/6, EGFR and KIT." (PMID 17910759, 2007). "Thus, KIT activation in GISTs may in part result from the presence of SCF within the tumours." (PMID 16570044, 2006). "The presence of both KIT and SCF has already been reported in several tumours, suggesting either an autocrine or paracrine oncogenic effect." (PMID 16570044, 2006). "In our microarray analysis, we found KIT in the ‘Down in N-SEM’ group, and the RT–PCR analysis in tumour samples confirmed this expression pattern." (PMID 15856041, 2005). "Patients with high c-KIT tumor expression had significantly shorter OS than those with low c-KIT tumor expression, regardless of BRCA and HRD status (HR: 1.71, 95% CI 1.16–2.53, P = 0.0071)." (PMID 41255967, 2025). "NGS of this tumor specimen was again negative for BRAF, KIT, NF1, and NRAS mutations, but was again notable for a missense mutation in EZH2 (c.2075 C > T, p.A692V)." (PMID 39984702, 2025). "In cases where the tumor morphology suggests an eGIST, but c-KIT expression is absent, the use of the DOG-1 marker is recommended to establish the diagnosis." (PMID 40539170, 2025). "Thus, for MC inhibition in the context of IgE‐dependent allergic or KIT‐driven neoplastic diseases, co‐inhibition of LYN, FYN, and KIT would be an evident advantage." (PMID 39676406, 2025). "Molecular profiling through next-generation sequencing (NGS) is essential for therapeutic planning; in our patient, the tumor was negative for BRAF, NRAS, and KIT mutations." (PMID 40937205, 2025). "The cell type-specific markers we used for cell annotation were as follows: T cell (CD3D); NK cell (KLRD1 and NKG7); plasma cell (IGKC and JCHAIN); Mast cell (KIT and TPSB2); tumour cell (CA9, NDUFA4L2 and SLC17A3); endothelium (PECAM1, PTPRB and KDR); mesangial cell (ACTA2 and PDGFRB)." (PMID 40830065, 2025). "In GISTs, FGFR2 expression has been reported at variable levels, particularly in tumors lacking KIT or PDGFRA mutations, suggesting a role in tumor progression independent of canonical drivers." (PMID 41150770, 2025). "Factors significantly associated with survival on univariable analysis were age, longest tumor diameter ≥2 cm, Patnaik Grade III, Kiupel high-grade, presence of HN3 lymph node metastases, Ki-67 index >23, aberrant KIT staining pattern, and administration of adjuvant therapy." (PMID 41234408, 2025). "Immunohistochemically, the tumor cells are negative for CD117/c-KIT, discovered on GIST 1, CD34, desmin, and S100." (PMID 40761993, 2025). "Besides, the KIT-d-MMAE group exhibited a lower Ki67 positivity compared to other groups, suggesting reduced proliferation of tumor cells." (PMID 40963922, 2025). "On multivariable analysis, Kiupel high-grade and tumor diameter of at least 2 cm were associated with a shorter overall survival time, while HN3 lymph node metastases, aberrant KIT staining pattern, and Ki-67 index >23 were not." (PMID 41234408, 2025).